TNF (tumor necrosis factor)
Diseases named in the same sentence as TNF in open-access papers (continued):
Sharing a sentence is not in itself a finding about the gene and the disease.
COVID-19 (continued). "Although we observed elevated levels of IL-1β and TNFα in some COVID-19 patients, this was not consistent across the cohort." (PMID 32909002, 2020). "Interestingly, it has been reported that levels of TNF-α and IL-1β, and some chemotactic cytokines (IL-8 and MCP-1) rise early in COVID-19 hypercytokinemia, facilitating a subsequent sustained increase in IL-6." (PMID 33292350, 2020). "Most patients with severe COVID-19 show significantly elevated serum levels of inflammatory cytokines, such as IL-6 and IL-1, as well as IL-2, IL-17, G-GSF, GM-GSF, IP-10, MCP1, MIP-1a (also known as CCL3), and TNF, known as a cytokine storm." (PMID 32983180, 2020). "Moreover, our data indicate that IFN treatment protects against worsening lung abnormalities in COVID-19 patients and limits the effects of SARS-CoV-2 infection on reducing CD8+ T cells and increasing IL-6 and TNF-α levels." (PMID 33396578, 2020). "TNF-α inhibitors, such as infliximab (Remicade) and adalimumab (Humira), were not applied in our patients due to the lack of related information in COVID-19 patients." (PMID 32733921, 2020). "When we compared historical and present control subjects who had normal cognition (no viral illness), we found that patients with COVID-19 and neurologic symptoms had increased CSF levels of IL-6, IL-8, IL-10, IP-10, and TNF-α." (PMID 32487282, 2020). "Interestingly, cytokines such as IL-1β, IL-6, TNF-α, and MCP-1 appear to be elevated in COVID-19 patients and also can induce HPSE expression." (PMID 33123154, 2020). "The activation of AP-1 and NF-κB signals caused an increased expression of inflammatory factors such as TNF-α, IL-1β, IL-8, MIP-1α and MIP-1β according to the KEGG enrichment analysis, which might be detrimental to COVID-19 rehabilitation." (PMID 33361761, 2020). "In support of these data, a study of 522 hospitalized COVID-19 patients reported a negative correlation between T cell numbers and serum IL-6, IL-10 and TNF-α levels." (PMID 32695122, 2020). "They found that the sum of TNF-α and IL10 combined could distinguish patients with PIMS apart from the patients with severe COVID-19, as they had higher levels than severe COVID-19 patients." (PMID 33344389, 2020). "In our study, we first showed that despite similar respiratory severity, plasma concentrations of numerous cytokines characterizing the “cytokine storm” (i.e. IL-1β, IL-6, IL-8, IL-15, TNF-α, CCL2, CCL4, CCL19, CCL20, TGF-α) were lower in COVID-19 compared to non-COVID-19 patients." (PMID 33272291, 2020). "In conclusion, ephedra-bitter almond may act against COVID-19 mainly through the PI3K-Akt signaling pathway, IL-17 signaling pathway, and TNF signaling pathway." (PMID 33292385, 2020). "Regarding the downregulated geneset, MHC II molecules, including HLA-DQA1, HLD-DRA, HLA-DRB1, HLA-DMB, HLA-DMA, etc., and cytokine/chemokine genes, including IL1B, TNF, CCL3, CCL4, and CXCL8 were expressed at lower levels in COVID-19 patients, especially those with severe diseases." (PMID 33101705, 2020). "Compared with non-HD patients with COVID-19, the proportion of T cell counting and plasma cytokines such as IL-4, IL-6, IL-10, TNF-α, and INF-γ was lower in HD patients infected by SARS-CoV-2." (PMID 32984768, 2020). "Since anti-inflammatory interventions that strongly supress immune function (e.g., anti-TNF therapeutics) are not recommended for treating COVID-19, we need to deploy other options that interfere with these barrier-disrupting mechanisms." (PMID 33101215, 2020). "SARS and COVID-19 do not lead to the upgrade of TNF-α, but the increase of IL-6 and IL-10 is more prevalent in COVID-19." (PMID 32754163, 2020). "COVID-19-specific cluster 3 genes were enriched by TNF/IL-1β-responsive genes whereas influenza-specific cluster 2 genes were enriched by IFN-I-responsive genes in addition to TNF/IL-1β-responsive genes, indicating that the IFN-I response is dominant in influenza compared to COVID-19." (PMID 32651212, 2020).
COVID-19 (continued). "Indeed, albeit to a non-viral stimulus, Zheng and colleagues found the frequencies of CD107a+, IFNγ+, TNFα+, and IL-2+ NK cells in PBMC samples acquired from COVID-19 patients were significantly lower following PMA and ionomycin challenge when compared to HCs." (PMID 33123152, 2020). "Reports also suggest that in certain instances, patients with severe COVID-19 were found to exhibit higher levels of pro-inflammatory cytokines such as IL-2R, IL-6, IL-8, IL-10, and TNF-α compared to patients with non-severe condition." (PMID 33120941, 2020). "Compared with COVID-19 without pneumonia, COVID-19 with pneumonia had significantly higher serum IL-2R, IL-6, and TNF-α." (PMID 32727465, 2020). "Compared with COVID-19 without pneumonia, COVID-19 with pneumonia had significantly higher serum interleukin (IL)-2R, IL-6, and tumor necrosis factor (TNF)-α." (PMID 32727465, 2020). "(b-c) Summarized are T-cell responses shown as % of IFN-γ and/or TNF-α+ cells in CD4+ or CD8+ T cells after subtraction of the negative controls in the COVID-19 patient at three longitudinal time points and in an age-matched healthy control (spike and M/N)." (PMID 33331820, 2020). "The known differences in pharmacokinetics and pharmacodynamics among anti-TNF drugs support the need for testing these agents in COVID-19-related ARDS and pneumonia patients without particular priorities, in order to identify the best option." (PMID 32527304, 2020). "This research has found flow cytometric profiles of increased IL-6, granulocyte-macrophage colony stimulating factor (GM-CSF), and IFN-γ in these severe patients, whereas TNF-α was not significantly up-regulated in CD4+ T cells from COVID-19 patients." (PMID 32350134, 2020). "A retrospective study of 21 patients identified significant elevations of plasma IL-6, IL-10, TNFα and IL-2 receptor in severe (n = 11) compared to moderate (n = 10) cases of COVID-19, whereas IL-1β and IL-8 levels were not significantly different." (PMID 32629875, 2020). "Therefore, we propose that anti-inflammatory strategies targeting not only inflammatory cytokines, including TNF, IL-1β, and IL-6, but also pathological IFN-I response needs to be investigated for the treatment of patients with severe COVID-19." (PMID 32651212, 2020). "For example, in a large cohort study, adult COVID-19 patients with recent anti-TNF exposure did not have increased rates of hospitalization or mortality compared with patients without recent anti-TNF exposure." (PMID 33551798, 2020). "Most COVID-19 patients had either no elevation or only mild increases in the major proinflammatory cytokines including TNF-α, IL-1α, IL-1β, IFN-ɣ, etc.." (PMID 32687484, 2020). "COVID-19 patients with pneumonia had higher levels of IL-2R, IL-6, and TNF-α than COVID-19 patients without pneumonia." (PMID 32727465, 2020). "We revealed that COVID-19 patients with pneumonia had significantly higher levels of serum IL-2R, IL-6, and TNF-α than COVID-19 patients without pneumonia." (PMID 32727465, 2020). "We obtained additional evidence of the IFN-I-potentiated TNF inflammatory response in severe COVID-19 by analyzing a gene module that is not responsive to IFN-I, but associated with TNF-induced tolerance to TLR stimulation." (PMID 32651212, 2020). "When comparing COVID-19 ARDS patients with HC, stimulation of PBMC by the overlapping S peptide pool led to a strong significant production of the Th1 or effector cytokines IFN-γ, TNF-α and IL-2 in COVID-19 ARDS patients." (PMID 32591408, 2020). "The “cytokine storm” concept is derived from the observation that COVID-19 patients requiring intensive care unit admission presented elevated circulating concentrations of CXCL10, CCL2, and TNFα as compared to those in which the infection was mild or moderate." (PMID 32983172, 2020).
COVID-19 (continued). "Most patients with severe COVID-19 exhibited significantly elevated levels of serum proinflammatory cytokines, including IL-6 and IL-1β as well as IL-2, IL-8, IL-17, G-CSF, GM-CSF, IP10, MCP1, MIP1-α (also known as CCL3), and TNF." (PMID 32984768, 2020). "In our study, well-documented hallmarks of severe COVID-19, such as lymphopenia, a higher neutrophil-to-lymphocyte ratio (NEU/LYM), and the proinflammatory cytokine storm including IL-6, IL-1β, IL-8, and TNF-α were observed in adult COVID-19 patients rather than pediatric patients." (PMID 39967737, 2025). "scRNA-seq on immunocytes in PMBCs from patients with healthy, mild, or severe COVID-19 and severe influenza found that while severe influenza patients primarily exhibited IFN responses, COVID-19 patients showed distinctive hyperinflammatory, TNF- and IL-1β-driven responses." (PMID 40742121, 2025). "Notably, in classical monocytes, type I IFN responses were present alongside TNF and IL-1β in patients with severe COVID-19 but not in mild COVID-19 cases." (PMID 40742121, 2025). "Furthermore, the majority of patients with severe COVID-19 exhibit markedly elevated serum levels of pro-inflammatory cytokines, including interleukin (IL)-6, IL-1β, IL-2, IL-8, IL-10, interferon (IFN)-α, IFN-γ, and tumor necrosis factor (TNF)." (PMID 41200104, 2025). "The presence of phosphorylated STING and high levels of ISGs and pro-inflammatory cytokines such as IL-1, IL-6, and TNF- α, especially in IFN-β-producing perivascular macrophages and damaged endothelial cells, were demonstrated in skin lesions of patients with moderate to severe COVID-19." (PMID 40649826, 2025). "Studies have established that increased levels of IL-1β, IL-2, IL-6, IL-10, IFN-γ, TNF, IFN-γ-inducible protein 10 (IP-10), granulocyte macrophage-colony stimulating factor (GM-CSF), and monocyte chemoattractant protein-1 (MCP-1) correlate with COVID-19 severity." (PMID 39940907, 2025). "The systemic inflammatory response observed in acute COVID-19, characterized by elevated levels of cytokines, such as IL-2, IL-10, IL-6, IL-8, C-Reactive Protein (CRP), and Tumor Necrosis Factor (TNF)-alpha, triggers acute phase reactions and, if sustained, may lead to end-organ damage." (PMID 40029921, 2025). "Therefore, it seems reasonable not to discontinue anti-TNF-α and anti-IL-17 medications during the hyperinflammatory state of COVID-19, since these medications do not seem to affect the course of the antiviral phase." (PMID 40142435, 2025). "The lack of GC responses in COVID-19, due to increased TNF and IL-6 expression and the rapid progress of WP disruption, result in loss of hypermutation process, which may impair the production of high-affinity antibodies in patients with severe disease." (PMID 41210940, 2025). "Since infliximab, an antibody targeting TNFα, and baricitinib, an inhibitor of the JAK/STAT pathway, correct the observed imbalance between eNOS and arginase, our findings suggest the potential efficacy of a combined therapy to counteract endothelial dysfunction in COVID-19." (PMID 40565379, 2025). "However, it is unclear whether TNF and IFN-γ levels are altered through TLR-dependent pathways and whether these pathways mediate disease severity during COVID-19." (PMID 39940907, 2025). "While not as abundant, indoxyl sulfate-induced TNF-α production and cell apoptosis may constitute an important part of the intricate immune network that leads to cytokine storm in severe COVID-19 cases." (PMID 39996729, 2025). "Moreover, the cytokines TNF, IL5, and IL10 have crucial roles in COVID-19 prognosis." (PMID 40766923, 2025). "Consequently, the administration of BDs of the mRNA COVID-19 vaccine was found to be safe, although transient alteration of systemic inflammation status is expected as a result of T cell priming (IL2-R, IL-6, TNF-α), followed by the deactivation (IL-10) of pro-inflammatory cytokine synthesis." (PMID 40266144, 2025).
COVID-19 (continued). "Previous studies have already shown that individuals with COVID-19 had high levels of some inflammatory mediators in more severe cases of the disease, such as C-reactive protein, D-dimer, bilirubin, urea, and IL-1β, IL-6, IL-8, IL-10, IL-18, IFN, TNF-α cytokines." (PMID 39861879, 2025). "A binary logistic regression model was applied to our data regarding the COVID-19 patients with chronic CVD using statins and COVID-19 patients with no cardiovascular co-morbidities, with statistically significant differences in IL-6, TNFα, and IL-10 concentrations." (PMID 39518552, 2024). "Besides, a prediction model based on age, BMI, fever duration, leucocyte count, lymphocyte proportion, proportion of CD3+ T cells, TNF-α, and IL-10 was constructed and internally validated here, which showed a good performance for predicting severe H1N1 infection in the post-COVID-19 era." (PMID 38566022, 2024). "Elevated levels of TNF-α, CXCL10, CCL2, and IL-10 in COVID-19 patients correlate with reduced populations of specific intestinal bacterial, which suggests that gut dysbiosis may contribute significantly to the development of intense and widespread inflammation." (PMID 38701071, 2024). "The inhibition of these cross-regulatory effects may account for the negative outcomes observed in our study, or it may suggest that TNF does not play a pivotal role in driving certain inflammatory responses in COVID-19 patients requiring hospitalization." (PMID 39459457, 2024). "Except for IL-8 decreased in the second trimester after infected with SARS-CoV-2, IL-2, TNF-α, TNF-β, IFN-γ, IL-4, IL-5, IL-6, IL-10, IL-17A, IL-17F, IL-22, IL-1β and IL-12p70 didn't change in the three trimesters between healthy pregnancies and pregnant women with COVID-19." (PMID 39113896, 2024). "Due to the attenuated immune response of COVID-19 patients, particularly the reduced upregulation of monocyte CD80 expression and the suppressed release of key cytokines such as IL-6, TNF, IL-1a, and IL-1b, this may lead to a decreased ability to clear C. albicans in these patients." (PMID 38658823, 2024). "The study identified IL-6, TNF, IL-1β, IL-10, and IL-2 as the five most distinctive cytokines that could effectively differentiate between individuals who had COVID-19 (including those with long COVID) and those who had never been exposed to the virus." (PMID 39518964, 2024). "Regardless of clinical outcome, patients in our COVID-19 cohort showed limited differences in most serum inflammatory markers, although the mean or median values of several markers, such as TNFα, ICAM-1, CRP, AAT, and ferritin, were higher in more severe patients." (PMID 38494528, 2024). "Similarly, a study conducted on patients with severe COVID-19 revealed that the levels of IL-2, IL-6, IL-10, and TNF-α were significantly higher compared to non-severe patients." (PMID 38355623, 2024). "In contrast to COVID-19, which showed markedly elevated plasma concentrations of 11 SMs, we observed decreased levels of several SMs, mainly pro-inflammatory cytokines (e.g., IFN-γ, IFN-α2, TNF-α, IL-7, IL-17A, and IL-15) in both the remission and acute phases of TTP." (PMID 39337495, 2024). "It has been shown that some parameters related to inflammation, such as TNFα, IL-6, interleukin-8 (IL-8), interleukin-10 (IL-10), CRP, white blood cell count (WBC), lymphocyte count (LC), and the number of neutrophils (NC) are correlated with the severity of COVID-19." (PMID 39335569, 2024). "Overall, our study shows that the development of CRS requires the involvement of multiple immune cells, and IL-2, TNF-α, and IFN-γ may act as the primary factors in triggering CRS, providing promising avenues for clinical interventions for patients with COVID-19." (PMID 39359733, 2024). "Therefore, the interplay between IL-2 and TNF-α/IFN-γ might be crucial in mediating the synergistic effect of IL-2 and spike protein in inducing CRS in patients with COVID-19." (PMID 39359733, 2024).
COVID-19 (continued). "Similarly, in a prior study assessing parenteral O3FA among COVID-19 patients, no significant variation in TNF-α levels was observed." (PMID 39339646, 2024). "IL-6 and TNFα were involved in immunological processes that had a direct and indirect relationship with the activation of cytokines, including IL6 and TNF-a, and cytokine storm, and this indicates their role in the formation of problems and complications, including ARDS, in COVID-19 patients." (PMID 39118801, 2024). "Considering the pronounced inflammatory response in COVID-19 and CDI infections, with elevated levels of IL-6, TNF-α, IL-1β, and IP-10, as well as the reported dysbiosis, FMT could play a crucial role in the treatment of CDI or more severe conditions like COVID-19 and C. difficile co-infections." (PMID 39432486, 2024). "Among patients with symptomatic COVID-19 (N = 240), hierarchical correlation matrices and force-directed network models identified two groups of strongly correlated mediators centered around IFN-α2/IFN-γ and TNF/lymphotoxin-α, respectively, with IL-15 appearing as a key inter-group mediator." (PMID 38368384, 2024). "COVID-19-positive patients presented a significant elevation of three (n = 3) of the following cytokines in plasma compared to negative controls: IL-1Ra, IP-10, and TNF-α." (PMID 38791465, 2024). "The phenomenon, called post-acute sequelae of COVID-19 (PASC), may be more closely linked to persistent cytokine dysregulation, including sustained IL-1β activity and elevated levels of IL-6 and TNF-α, rather than the emergence of post-COVID-19 autoantibodies." (PMID 39518964, 2024). "The serum concentration of TNF-α and IL-1β levels did not change among COVID-19 patients." (PMID 37363608, 2023). "Nevertheless, another study showed that in paediatric/young COVID-19 patients (n = 65, < 24 years) who generally suffer less severe disease there were increased serum levels of IFNγ and IL-17A but not of IL-6 and TNFα protein compared to adult COVID-19 patients (n = 65)." (PMID 36941580, 2023). "However, COVID-19 vaccine-induced antibody responses are diminished relative to healthy controls in patients with IBD taking anti-TNF and JAK-inhibitor therapies, but not anti-integrin or thiopurine monotherapy, following two and three vaccine doses." (PMID 37842172, 2023). "Similarly, TNF and IL-17A were upregulated with COVID-19 in non-pregnant patients and only showed a slight tendency to increase during pregnancy." (PMID 37016066, 2023). "Several proinflammatory cytokines such as tumor necrosis factor-alpha (TNF-α), interleukin (IL)-6, IL-2, IL-7, and IL-10 are involved in the development of cytokine release syndrome (CRS), which then contributes to the high morbidity and mortality of COVID-19 including ARDS." (PMID 37047115, 2023). "Several studies have documented significant elevation in inflammatory cytokines (IFN-γ, TNF-α, IL-6) in severe COVID-19 compared to non-severe cases that are consistent with this study and may be proposed as prognostic markers." (PMID 38057707, 2023). "Interleukin (IL) 2 and 6 (IL-2, IL-6), tumor necrosis factor-alpha (TNF-α), interferon-gamma (IFN-γ), macrophage inflammatory protein (MIP), and monocyte chemoattractant protein 1 (MCP-1) are among many other cytokines that are present in seriously ill COVID-19 patients." (PMID 36901751, 2023). "The anti-inflammatory properties of honey on proinflammatory cells and agents by the modulation and reduction of TNF, NF-kB pathways, PI3K/Akt, MAPK, T-Lymphocyte, B-Lymphocyte, RAS, and apoptosis signaling pathways could lead to a prevention of COVID-19 penetration and reproduction in host cells." (PMID 37631069, 2023). "Amiodarone and COVID-19 share similar pathophysiology toward the development of pulmonary fibrosis through the upregulation of the renin-angiotensin-aldosterone system (RAAS) and cytokines (interleukin (IL)-1, IL-8, tumor necrosis factor (TNF)-α, and transforming growth factor (TGF)-β)." (PMID 36843772, 2023).